ZEB2 (zinc finger E-box binding homeobox 2)
Diseases named in the same sentence as ZEB2 in open-access papers (continued):
Sharing a sentence is not in itself a finding about the gene and the disease.
liver disease (5 papers, 2020 to 2025). "A subsequent genome-wide association study (GWAS) identified shared single-nucleotide polymorphisms (SNPs) in the genes AR, EDIL3, MACROD2, PCSK5, RUNX1T1, TENM4, and ZEB2 between PN and liver disease from the FinnGen cohort." (PMID 38397136, 2024). "The different and sometimes opposite roles for Zeb2 in different liver cell types definitely implies that using Zeb2 as a target for treating liver disease will require a cell type-specific approach." (PMID 33909875, 2022). "Of them, lnc-ZEB2-19 had the highest AUC in all three comparisons, indicating a significant correlation between lnc-ZEB2-19 exosomal expression and hepatic diseases." (PMID 32554864, 2020). "Thus, TFs involved in LSEC differentiation have different effects on the development of steatosis, and ZEB2 has a challenge-type dependent role in liver disease." (PMID 40603966, 2025). "In addition, we conclude that endothelial ZEB2 has a stage-dependent effect on liver disease, which will necessitate customized approaches when considering ZEB2 as a target for therapy." (PMID 40603966, 2025). "The disease-promoting role of endothelial ZEB2 in early MASLD as opposed to its protective role in fibrosis underscores a context-dependent effect in liver disease." (PMID 40603966, 2025).
lymph node metastasis (5 papers, 2015 to 2021). "Clinical and pathologic evaluation revealed a potential association between ZEB2 positivity and lymph node metastasis and higher-stage disease (eTable 4 in the Supplement)." (PMID 30646224, 2018). "As lymph node metastasis is highly associated with poor prognosis, we determined the association between the co-expression of TWIST1 and ZEB2 and patient survival in lymph node positive and negative patients separately." (PMID 26214683, 2015). "Notably, co-expression of TWIST1 and ZEB2 in OSCC was significantly associated with poorer overall survival, particularly in patients without detectable lymph node metastasis." (PMID 26214683, 2015). "Notably, co-expression of TWIST1 and ZEB2 was significantly prevalent in OSCC patients with poorer overall survival particularly in patients with no lymph node metastasis." (PMID 26214683, 2015). "Remarkably, co-expression of TWIST1 and ZEB2 was correlated with poorer overall survival in OSCC, particularly in patients with no lymph node metastasis." (PMID 34567183, 2021).
metastatic cancer (5 papers, 2011 to 2023). A carcinoma which has spread from the original site of growth to another anatomic site. "Results revealed a higher Mesenchymal markers in primary cancer cells (e.g., NCAM1, LAMB1, SERPINE1, TCF4, VIM, ZEB1, and ZEB2) and a higher Epithelial markers in metastatic cancer cells (e.g., CDH1, CLDN4, ELF3, EPCAM, KRT18, KRT7, and KRT8)." (PMID 37202394, 2023). "Based on the HNSCC samples, the high expression of ZEB1 and ZEB2 was associated with advanced and metastatic cancer, and high levels of ZEB1 and ZEB2 predicted poor outcome." (PMID 30755200, 2019). "Taken together, these data suggest that ZEB2 is a central transcriptional regulator, which controls gene expression necessary for the progression of metastatic cancer." (PMID 21303533, 2011). "Therefore, these Sp1 inhibitors may have a therapeutic potential for the treatment of ZEB2-dependent metastatic cancers." (PMID 29416649, 2018). "Several transcription factors, such as SNAIL, SLUG, ZEB1, and ZEB2/SIP1, participate in the repression of epithelial markers (E-cadherin) and the conversion of epithelial-like cancer cells into metastatic cancer cells." (PMID 30544763, 2018).
metastatic tumors (5 papers, 2016 to 2025). "Meanwhile, the level of E-cadherin protein decreased, while the levels of N-cadherin, Snail, Slug, ZEB1, and ZEB2 proteins increased, in metastatic tumors with FOXM1 knockdown." (PMID 32513952, 2020). "Members of the Snail family of transcriptional repressors (e.g., SNAIL and SLUG) and other repressors of E-cadherin gene expression, such as ZEB1, ZEB2, and TWIST1, have been detected at EMT sites at the leading edge of metastatic tumors." (PMID 40490818, 2025). "Note that expression of SNAIL2, ZEB1, ZEB2, TWIST2 was significantly lower in the distant metastatic tumors (Met_distant, n = 628) than other subgroups." (PMID 35272617, 2022). "We found epithelial marker genes, Krt18, Epcam, Dsp, were downregulated in the metastatic tumors, while genes that promote EMT, Zeb2, Loxl2, and Plau were upregulated." (PMID 31881983, 2019).
acute lymphoblastic leukemia (4 papers, 2015 to 2025). Leukemia with an acute onset, characterized by the presence of lymphoblasts in the bone marrow and the peripheral blood. "In addition, sustained ZEB2 expression has been shown to promote B and T acute lymphoblastic leukemia (ALL) and AML." (PMID 33327558, 2020). "Enhanced expression of ZEB2 has been identified in patients with early T-cell precursor Acute Lymphoblastic Leukemia (ETP-ALL), a particularly poor outcome subtype of T-ALL." (PMID 37600794, 2023).
COVID-19 (4 papers, 2022 to 2024). A disease caused by infection with severe acute respiratory syndrome coronavirus 2. "It is also notable that many of the transcriptional signatures, including RHOB, MPP6, TNFRSF1B, ITGB2, and ZEB2 elevated in AM2 from COVID-19 patients have also been detected as transcriptional markers of AM B cells." (PMID 35899045, 2022).
cutaneous melanoma (4 papers, 2017 to 2023). A primary melanoma arising from atypical melanocytes in the skin. "The role of ZEB2 was confirmed in another study, in which human primary cutaneous melanoma samples with high nuclear ZEB2 staining were associated with a better prognosis than tumours with low nuclear ZEB2 staining." (PMID 35682684, 2022). "Normal cutaneous melanocytes have a high expression of SNAI2 and ZEB2 and a low expression of ZEB1 and TWIST1, while malignant cutaneous melanomas have low SNAI2 and ZEB2 and high ZEB1 and TWIST1." (PMID 35682684, 2022).
keloid (4 papers, 2019 to 2024). An irregularly shaped, elevated mark on the skin caused by deposits of excessive amounts of collagen during wound healing. "In the skin, ZEB2 has been linked with hyperproliferation of the epidermis and upregulation in keloid tissue." (PMID 38397136, 2024). "Immunofluorescence had revealed that ZEB2 were markedly higher expressed in keloid tissues than normal skin tissue." (PMID 31652445, 2019). "Expression of miR-1587 and miR-2392 were significantly down-regulated in keloid tissues and HSFBs, while the ZEB2 was a target of both and up-regulated in keloid tissues and HSFBs compared with the normal controls." (PMID 31652445, 2019). "Further exploration had found that both expression levels of miR-1587 and miR-2932 were negatively correlated with the expression of ZEB2 in keloid tissues." (PMID 31652445, 2019). "In this study, ZEB2 was identified to be a target of miR-1587 and miR-2392 and significantly up-regulated in keloid tissues." (PMID 31652445, 2019). "In conclusion, miR-1587/miR-2392 played an inhibitive role in the progression of keloids, and ZEB2, which could be targeted by miR-1587/miR-2392, played a promotive role in the development of keloids." (PMID 31652445, 2019). "Quantitative real-time PCR (RT-qPCR) analysis had detected that the expression levels of miR-1587 and miR-2392 were significantly down-regulated in keloid tissues, but ZEB2 expression level was significantly up-regulated in keloid tissues compared with the normal skin tissues." (PMID 31652445, 2019). "Considering these, the correlations between BTXA and miRNAs in treating keloids were explored in the present study and found that BTXA was identified to regulate the expression of miR-1587 and miR-2392, and their targeted ZEB2 in HSFBs." (PMID 31652445, 2019). "BTXA could significantly down-regulate the expression of ZEB2 via up-regulating the expression of miR-1587/miR-2392 to suppress the proliferation and EMT but increase cell apoptosis and autophagy of HSFBs, to attenuate the development of keloids." (PMID 31652445, 2019).
Obesity (4 papers, 2012 to 2025). Accumulation of substantial excess body fat. "Mmu-miR-200b and mmu-miR-200c(members of the mmu-miR-200 family), mmu-miR-203 and mmu-miR-192 target Zeb1 and Zeb2 that regulate epithelial to mesenchymal transition and have recently been implicated in adipogenesis and obesity." (PMID 22496873, 2012). "For a more complete view on endothelial Zeb2 expression, we expanded our analysis with extra-hepatic vascular beds from other metabolically demanding organs or organs with sinusoidal ECs and analyzed its expression in steatotic livers from patients with obesity or mice exposed to WD." (PMID 40603966, 2025). "Furthermore, the analysis of a cohort of 112 CMS2 CRC patients showed a significant negative correlation between ZEB2 expression and RFS probability, suggesting that ZEB2 is a putative prognostic factor that could be relevant in cancer patients affected by obesity." (PMID 34408135, 2021).
ovarian tumors (4 papers, 2015 to 2024). "In renal and ovarian tumour models, it targets ZEB2 and RhoA and mediates TGF-beta-induced EMT." (PMID 38801504, 2024). "We described that ZEB2 was expressed in the cytoplasm in the inner part of the ovarian tumors." (PMID 26136338, 2015). "Interestingly, the mean expression of the three genes (TYMS, ZEB2, and MDM2) was upregulated in all ovarian tumor subtype analyzed." (PMID 30038317, 2018).
retinoblastoma (4 papers, 2017 to 2022). A malignant tumor that originates in the nuclear layer of the retina. "Although accumulating evidences have suggested the oncogenic role of ZEB family, some researchers put forward that ZEB2 can suppress tumor by interacting with retinoblastoma pathway as well." (PMID 28416756, 2017). "In retinoblastoma, LINC00152 is activated by SP1 to inhibit miR-30d and thus regulate the expression of SOX9 and ZEB2 to promote tumor recurrence." (PMID 36033524, 2022). "Besides, different signaling pathways are involved and ZEB2 was reported to act as a tumor suppressor in some cancers via mediating the TGF-beta regulated repression of hTERT and interacting with retinoblastoma pathway." (PMID 28416756, 2017).
squamous carcinoma (4 papers, 2015 to 2023). "A previous report indicated that Akt activation can upregulate Snail and Zeb2 and promote EMT in squamous cell carcinoma." (PMID 27455254, 2016).
atherosclerosis (3 papers, 2023 to 2025). A disease characterized by the build-up of fatty material and calcium deposition in the arterial wall resulting in partial or complete occlusion of the arterial lumen. "The differential DNAme also comprised key gene expression modulators, such as TNRC6B, a component of the miRISC, and ZEB2, a key transcription factor in embryogenesis, wound healing, and hematopoietic differentiation and epigenetic modulator of the transcription of atherosclerosis-associated genes." (PMID 40662355, 2025).
autoimmune disease (3 papers, 2025). A disorder resulting from loss of function or tissue destruction of an organ or multiple organs, arising from humoral or cellular immune responses of the individual to their own tissue constituents. "ZEB2 can also mediate the presentation of both cytotoxic phenotype and B cell helper functions in a newly designated T cell subtype, “age-associated T helper (ThA) cells”, a distinct CXCR3midCD4+ effector memory T cell population that expands in various autoimmune diseases." (PMID 40510028, 2025). "ZEB2 is essential for age-associated B cell accumulation and function by repressing MEF2B and Itgax, presenting as a powerful driver for B cell autoimmunity and a potential target for intervention in autoimmune disease." (PMID 40510028, 2025). "A recent study showed that inhibition of the critical transcription factor ZEB2 in ABCs could alleviate lupus pathogenesis, suggesting the therapeutic potential of targeting ABCs in autoimmune disease." (PMID 41188893, 2025). "Notably, AtM B cells were also featured with the high expression of ZEB2, TBX21, and SREBF2, consistent with specific TFs of age-associated B cells (ABCs) in autoimmune diseases." (PMID 41459486, 2025).
Autoimmunity (3 papers, 2022 to 2025). The occurrence of an immune reaction against the organism's own cells or tissues. "Altogether, we found deletion of genes associated with autoimmunity mediated early hematopoiesis (e.g. ZEB2) and influenced the inflammatory potential (e.g. ICAM1, LSP1 and PRKCB) of iPSC-derived myeloid cells, coinciding with the expected phenotype." (PMID 35610203, 2022). "We therefore examined whether ZEB2 regulated ABC-mediated autoimmunity in lupus induced by IMQ, a TLR7 agonist." (PMID 38271512, 2024). "Thus, ZEB2 is essential for ABC-mediated autoimmunity and the proinflammatory properties of ABCs." (PMID 38271512, 2024).
B-cell non-Hodgkin lymphoma (3 papers, 2014 to 2025). The most common type of non-Hodgkin lymphoma. "It has recently been reported that NOTCH2, activated via delta-like ligand 1, inhibits the EBV lytic cycle in the EBV-infected B-cell non-Hodgkin's lymphoma line by upregulating the cellular transcription factor Zeb2, which represses BZLF1 expression." (PMID 26018735, 2015). "Activated Notch-2 also inhibited EBV entry into the lytic cycle in a B cell non-Hodgkin's lymphoma line by upregulating the cellular transcription factor Zeb2, which represses the transcription of BZLF1." (PMID 25122803, 2014).
Cerebral ischemia (3 papers, 2019 to 2022). Restriction of arterial blood supply to the brain associated with insufficient oxygenation to support the metabolic requirements of the tissue. "Zinc finger E-Box binding homeobox 2 (ZEB2)-induced astrogliosis is competent to protect neuron through retarding pyroptosis in cerebral ischemia." (PMID 35000541, 2022). "ZEB2 was found up-regulated in cerebral ischemia reperfusion injury rats, further increased expression of ZEB2 attenuated the cerebral ischemia reperfusion injury, whereas knockdown of ZEB2 increased lesion size of cerebral ischemia reperfusion." (PMID 34852714, 2021). "However, the role of ZEB2 in neural regeneration after cerebral ischemia reperfusion is unknown." (PMID 34852714, 2021).
Cirrhosis (3 papers, 2012 to 2023). A chronic disorder of the liver in which liver tissue becomes scarred and is partially replaced by regenerative nodules and fibrotic tissue resulting in loss of liver function. "The expression levels of lnc-GPR89B-15 and lnc-ZEB2-19 verified by qPCR were consistent with RNA-seq results in hepatitis, cirrhosis, and HCC groups." (PMID 32554864, 2020). "In addition, we examined the expression distribution of SNAI1, ZEB2, and VIM, which are the top three markers exhibiting strong correlation with KLF2, in the GSE25097 dataset related to cirrhosis development." (PMID 37386390, 2023).
fibrosis (3 papers, 2017 to 2022). the formation of excess fibrous connective tissue in an organ or tissue in a reparative or reactive process. "In agreement with the reported correlation between fibrosis progression and angiogenesis, CCl4-induced fibrosis was accompanied by vascular expansion (average increase in Pan-endo area of 44 ± 6%), however, this angiogenic response was not boosted by endothelial Zeb2-KO." (PMID 33909875, 2022). "ZEB2 is also regulated by TGF-β and other miRNA species such as members of the miR-200 family which are not affected in our fibrosis model." (PMID 33396535, 2020).
ischemia (3 papers, 2021 to 2022). A hypoperfusion of the BLOOD through an organ or tissue caused by a PATHOLOGIC CONSTRICTION or obstruction of its BLOOD VESSELS, or an absence of BLOOD CIRCULATION. "Zinc Finger E-Box Binding Homeobox 2 (ZEB2) promoted activation of astrocytes or astrogliosis, which protected neurons by alleviating pyroptosis in ischemia-caused central nervous system injury." (PMID 36211509, 2022). "Here we show by gain- and loss-of-function studies that ZEB2 confers cardioprotective effects after ischemia via an increase in circulating levels of TMSB4 and PTMA7–9." (PMID 33398012, 2021). "Also, ZEB2 overexpression in vivo significantly recovered neural injury caused by ischemia." (PMID 34852714, 2021). "Here, we show that the transcription factor Zinc finger E-box-binding homeobox 2 (ZEB2) is increased in stressed cardiomyocytes and induces a cardioprotective cross-talk between cardiomyocytes and endothelial cells to enhance angiogenesis after ischemia." (PMID 33398012, 2021).
ischemic stroke (3 papers, 2019 to 2025). A stroke disorder caused by obstruction of blood flow to the brain, due to thrombotic (local blood clot formation) or embolic (due to a blood clot or other material traveling from another site) event. "Our results establish that ischemic stroke-mediated stabilization of HIF1α induces the expression of ZEB2." (PMID 31784544, 2019). "We observed elevated expression of ZEB2 and TRPC6 in glomerular podocytes from ischemic stroke rats." (PMID 31784544, 2019).
latent infection (3 papers, 2016 to 2022). "Quantifying the cluster membership demonstrated a trend that those cells with higher expansion levels were located in cluster 1 for acute, 5 for chronic, 2 for latent infection, which characteristically expressed Zeb2, Tox, and Klrg1, respectively." (PMID 35185882, 2022).
lupus (3 papers, 2022 to 2025). "To investigate how ZEB2 impacts pathogenic ABCs, we investigated the consequences of Zeb2 deficiency in B cells using two lupus mouse models (lupus induced by the TLR7 agonist imiquimod (IMQ) and bm12 cell transfer) as well as an acute LCMV infection model." (PMID 38271512, 2024). "Published transcriptomic datasets had reported several candidates such as ZBTB32, SOX5, BHLHE40, TOX and ZEB2 that were upregulated in human and mouse ABCs, especially ZEB2 which has been proposed to control ABC formation in lupus." (PMID 36072594, 2022). "In mice with TLR7-driven lupus, ZEB2 is essential for ABC formation and autoimmune pathology." (PMID 38271512, 2024).
myocardial infarction (3 papers, 2021 to 2026). Gross necrosis of the myocardium, as a result of interruption of the blood supply to the area, as in coronary thrombosis. "Cardiomyocyte-specific deletion of ZEB2 results in impaired cardiac contractility and infarct healing post-myocardial infarction (post-MI), while cardiomyocyte-specific ZEB2 overexpression improves cardiomyocyte survival and cardiac function." (PMID 33398012, 2021).
prostate adenocarcinoma (3 papers, 2021 to 2025). "Consistently, the co-expression analysis in TCGA PanCancer Atlas revealed that SCAND1 and MZF1 expression was negatively correlated with EMT driver genes, including CTNNB1, ZEB1, ZEB2 and TGFBRs, in prostate adenocarcinoma specimens." (PMID 36552758, 2022).
thyroid cancer (3 papers, 2014 to 2022). "However, overexpression of ZEB2 is associated with oncogenic transformation and tumor metastasis in several cancer types such as endometrial, hepatocellular, and thyroid cancers." (PMID 36704357, 2022). "Increased expression of Snail, Slug, Twist, ZEB1, and ZEB2 expression in thyroid cancers has been well demonstrated." (PMID 25076938, 2014).